STAT3 (signal transducer and activator of transcription 3)
Diseases named in the same sentence as STAT3 in open-access papers (continued):
Sharing a sentence is not in itself a finding about the gene and the disease.
skin cancer (continued). "Although some researches support its antitumor activity, some others suggest that it promotes the growth and development of different types of cancer including skin cancer by activation of STAT3." (PMID 34239554, 2021). "The expression of p-STAT3 in A431 (skin cancer) is highly upregulated compared to HEKn (normal skin cell)." (PMID 33669832, 2021). "IL-17 and IL-22 produced by Th17 cells enhance skin cancer promotion by activating STAT3 in stromal cells and tumors and by increasing the infiltration of myeloid cells in skin cancer environments." (PMID 33917793, 2021). "In particular, it has been reported that STAT3 is essential for the skin cancer development, and aberrant activation of STAT3 occurs in skin cancer." (PMID 33669832, 2021). "In particular, the formation of the RAF1–ROK-α complex in chemically induced murine skin carcinoma models allows the activation of STAT3 (Signal transducer and activator of transcription 3), and MYC (Myelocytomatosis) and cell de-differentiation." (PMID 33920182, 2021). "Studies have shown that STAT3 plays a critical role in the development of either chemically or UVB-induced skin cancer by promoting the survival and proliferation of keratinocytes during carcinogenesis." (PMID 30208623, 2018). "Our findings implied that TC-PTP is a potential novel target for the prevention of skin cancer through its role in the regulation of STAT3 and AKT signaling." (PMID 30208623, 2018). "In mouse skin cancer formation and maintenance, signal transducer and activator of transcription 3 (Stat3) is activated by Runx1 signaling as a tumor promoter." (PMID 30046048, 2018). "Runx1 acts is a tumor promoter in mouse skin cancer formation and maintenance by promoting Stat3 activation and Tgfb3 expression is often upregulated in cancer formation." (PMID 30046048, 2018). "Topical iontophoresis of curcumin with STAT3 siRNA complex enhanced skin penetration of the nanocomplex and can be developed for skin cancer treatment." (PMID 30366360, 2018). "STAT3 (signal transducer and activator of transcription 3) is an oncogenic transcription factor which is activated in multiple cancer types, including skin cancer." (PMID 30366360, 2018). "It is the continuous activation of STAT3 by the repeated/long-term exposure to TPA that contributes to the development of skin cancer." (PMID 28322331, 2017). "Our previous studies using epidermal specific TC-PTP knockout mice indicated that TC-PTP can play a role in attenuating chemically-induced skin cancer formation by negatively regulating STAT3 and AKT signaling." (PMID 29207596, 2017). "Studies have shown that STAT3 contributes to enhanced skin cancer formation in UVB-induced carcinogenesis by regulating its target gene expression." (PMID 29207596, 2017). "Our findings reveal that TC-PTP has potential as a novel target for the prevention of skin cancer through its role in the regulation of STAT3 and AKT signaling." (PMID 28322331, 2017). "The extract from the UE demonstrated the ability of inhibiting both cancer cell proliferation and metastasis by downregulating the skin tumor-promoting genes such as Bcl-2, STAT3, and MMP-9." (PMID 29065632, 2017). "There are only limited studies on the involvement of the other IL-6 family cytokines in skin cancer, though we now know that IL-11 is over-expressed in skin tumors and promotes tumor development through the activation of STAT3." (PMID 31051015, 2016). "Meanwhile, the levels of the gene sets for epithelial-mesenchymal transition (EMT), Jak-Stat3, Cyclin D1, and Skin cancer progression were also elevated in HaCaT-Piwil2 cells, indicating neoplasia transformation." (PMID 27602489, 2016). "One of the targets of STAT3 signaling in skin cancer development is Bcl-xL, whose ablation resulted in marked reduction in skin tumor load." (PMID 31051015, 2016).
skin cancer (continued). "IL-17, in conjunction with IL-22 that are both produced by Th17 cells, supports the development of skin cancer by activating STAT3 in tumor and stromal cells and promoting the infiltration of myeloid cells into the tumor microenvironment." (PMID 31051015, 2016). "The greater ability of 3-epiCA and MA to inhibit skin tumor promotion was associated with greater reduction of Cox-2 and Twist1 proteins and inhibition of activation (i.e., phosphorylation) of IGF-1R, STAT3 and Src." (PMID 26513295, 2015). "Given its significant role throughout the skin carcinogenesis process, Stat3 is an attractive target for skin cancer prevention and treatment." (PMID 23577258, 2013). "Collectively, these studies demonstrate that Stat3 plays a critical role in the development of UVB-induced skin tumors through its effects on both survival and proliferation of keratinocytes." (PMID 23577258, 2013). "Further studies using a transgenic mouse model with a gain of function mutant of Stat3 (Stat3C) expressed in the basal layer of the epidermis revealed a novel role for Stat3 in skin tumor progression." (PMID 23577258, 2013). "The critical role of Stat3 in skin tumor development was further supported by data obtained from a transgenic mouse model in which a constitutively active mutant of Stat3 called Stat3C, was expressed in skin under the control of the keratin-5 promoter." (PMID 16603078, 2006). "Inhibitors of JAK and STAT3 have shown strong preclinical antitumor activity against skin cancers." (PMID 40399946, 2025). "In addition, upregulation of JAK/STAT3 signaling was found globally across the immune cell types in skin tumors." (PMID 40282557, 2025). "In addition, skin tumor progression dramatically upregulated Jak2/Stat3 expression and the interferon response across various immune cell clusters." (PMID 40282557, 2025). "In addition, skin tumor progression dramatically upregulated JAK/STAT3 expression and the interferon response across various cell types." (PMID 40282557, 2025). "Liposomes containing curcumin and STAT3–siRNA have been developed to treat skin cancer." (PMID 38919334, 2024). "Moreover, the transcription activity of miR-383 has also been reported to be downregulated by signal transducer and activator of transcription 3 (STAT3) in human skin cancer." (PMID 34976192, 2022). "Importantly, similar to that observed in SmoM2 murine skin tumors, blockade of STAT3 in our mouse model resulted in significant disruption of Smo‐driven MB tumor induction." (PMID 34482626, 2022). "Recently, a study shows that DHODH, playing a critical role in UVB-induced energy metabolism reprogramming, is upregulated mainly resulting from transcriptional activation by signal transducer and activator of transcription 3 (STAT3) in a multistage model of UVB radiation-induced skin cancer." (PMID 33971967, 2021). "Since Stat3 is an oncogenic transcription factor that plays a role in malignant conversion of skin tumors and is important for the phases of tumor initiation and promotion, p38δ might promote skin carcinogenesis (in part) through the activation of Stat3." (PMID 33923030, 2021). "The data showed that STAT3 expression was correlated with sensitivity to bafilomycin A1 in skin cancer cell lines, and STAT3 might play a role in autophagy in skin cancer." (PMID 32486001, 2020). "Skin cancer can besuppressed by blocking aberrant expression of STAT-3." (PMID 32167126, 2020). "Interestingly, it has been shown that STAT3 down-regulated the expression of miR-383 in a skin cancer cell line." (PMID 31847355, 2019). "Indeed, Stat3-deficient mice were resistant to UVB-induced skin carcinogenesis and, inversely, the formation of skin tumors was accelerated in mice overexpressing STAT316." (PMID 31551419, 2019). "In addition to the regulation of cell survival, STAT3 contributes to UVB-induced skin cancer formation by promoting cell proliferation." (PMID 29207596, 2017).
skin cancer (continued). "Thus, inhibition of aberrantly overactivated STAT3 signaling is considered as a pragmatic approach for achieving the prevention of skin cancer." (PMID 28912452, 2017). "Overall, our results indicate that UVB-induced TC45 nuclear translocation by the AKT/14-3-3σ axis allows for the dephosphorylation of STAT3, leading to increased apoptosis and decreased cell proliferation of keratinocytes, which can contribute to the prevention of skin cancer development." (PMID 29207596, 2017). "Our findings suggest that the reoccurring activation of TC-PTP during tumor promotion could continuously inhibit STAT3 phosphorylation/activation and thereby contribute to the prevention of skin cancer." (PMID 28322331, 2017). "Recent studies have shown that activation of STAT3 might be a predominant factor in the development of UVB-induced skin tumors by promoting keratinocyte survival and proliferation." (PMID 29207596, 2017). "In addition to IL-22, IL-6 and IL-11 also drives the malignant progression of skin cancer cells through the activation of STAT3 and upregulation of inflammatory and angiogenic factors." (PMID 31051015, 2016). "Beyond HH signaling pathway, recently other signaling pathways such as STAT3 signaling pathway involve in BCCs carcinogenesis, during the development of ultraviolet (UV) B skin tumors, STAT3 plays a critical role in both survival and proliferation of keratinocytes." (PMID 27049829, 2016). "However, the greater ability of 3-epiCA and MA to inhibit skin tumor promotion was associated with greater reduction of Cox-2 and Twist1 proteins and inhibition of activation (i.e., phosphorylation) of IGF-1R, STAT3 and Src." (PMID 26513295, 2015). "The critical role of Stat3 in skin tumor development was further supported by data obtained from the K5.Stat3C transgenic mouse model in which the DiGiovanni and Clifford research groups expressed the Stat3C protein in skin under the control of the keratin-5 promoter." (PMID 22704648, 2012). "A previous study has shown the retinoic acid suppressed Stat3 phosphorylation in skin cancers." (PMID 21266059, 2011). "Stat3 has a critical function in the development of skin cancer." (PMID 21595927, 2011). "Collectively, our studies suggest that inactivation of phosphatases such as TC-PTP due to aberrant signaling pathways could lead to constitutive activation of Stat3, contributing to the development of cancers including skin cancer." (PMID 20421975, 2010). "With regard to chemically-mediated skin carcinogenesis, Stat3-deficient mice were completely resistant to development of skin tumors induced by the two-stage carcinogenesis regimen and abrogation of Stat3 function by using a Stat3-specific decoy oligonucleotide inhibited the growth of skin tumors." (PMID 20421975, 2010). "In addition to its recently discovered roles in the development and progression of skin tumors induced by two-stage carcinogenesis, Stat3 also plays an important role in UVB-mediated skin carcinogenesis." (PMID 20421975, 2010). "We have shown that Stat3 activation is required for skin tumor formation following UVB exposure." (PMID 20421975, 2010). "In particular, Stat3 plays a critical role in the development of skin cancer." (PMID 16603078, 2006). "Recent studies have provided convincing evidence for a critical role for Stat3 in every stage of mouse skin cancer development, from promoting the survival of initiated cells to conferring late-stage malignant characteristics such as enhanced motility and invasiveness." (PMID 16603078, 2006). "In an experimental two-stage mouse skin chemical carcinogenesis model it has been shown that Stat3 is constitutively activated in skin tumors, and that activated Stat3 is indispensable for both the initiation and the promotion stages of epithelial carcinogenesis." (PMID 16603078, 2006). "In addition, M2-like macrophages were consistent with elevated STAT3 signaling in skin tumors." (PMID 40282557, 2025).
skin cancer (continued). "Recently, it was shown that constitutively active STAT3 signalling significantly changes the behaviour of keratinocyte stem/progenitor cells residing in the hair follicle, and that disruption of STAT3 in keratinocytes compromises wound-healing and affects initiation and promotion of skin tumours." (PMID 35406439, 2022). "Furthermore, Runx1 maintained Stat3 activity in the epidermis and in skin cancer cells." (PMID 30046048, 2018). "Finally, local or systemic JAK/STAT inhibition by tofacitinib could be crucial for the development of optimized therapeutics also for the treatment of skin tumors characterized by aberrant IL-22 signaling and STAT3 activation in keratinocytes." (PMID 30581877, 2018). "It has been demonstrated that TC-PTP gets activated following irradiation with UVB and mediates STAT3 dephosphorylation, thus deactivating the STAT3 signaling pathway and preventing UVB-induced skin cancer formation." (PMID 40021617, 2025). "Gene set variation analysis showed that enriched gene signatures in skin tumors included the interferon-gamma response, the interferon-alpha response, and JAK/STAT3 signaling." (PMID 40282557, 2025). "Though STAT3 activation and CD5+ B cell proportion are correlated with poor outcomes in B16 skin tumor cell lines, adoptive transfer of activated B cells in tumor cell inoculated mice leads to slower tumor growth." (PMID 36033455, 2022). "Our group recently showed that the inflammatory signal transducer and activator of transcription 3 (STAT3) pathway is highly active in K14-HPV8-CER murine skin and that keratinocyte-specific STAT3 heterozygosity interferes with skin tumour development." (PMID 35406439, 2022). "Using a multistage model of UVB radiation-induced skin cancer, we show that UVB-induced DHODH upregulation is mainly regulated transcriptionally by STAT3." (PMID 31551419, 2019). "Epidermal specific ablation of STAT3 resulted in dramatically reduced skin tumor load, in both oncogene- and UVR-driven mouse models of skin cancers." (PMID 31051015, 2016). "STAT3 is a key regulator of keratinocytes in response to UVB irradiation and plays an important role in initiation, promotion and progression of skin cancer." (PMID 25268165, 2014). "Although the in vivo test on IL-6 in mouse models of skin cancer is lacking at this point, cell line-based studies have shown that IL-6 plausibly promotes skin tumor growth through activation of the STAT3 transcription factor." (PMID 31051015, 2016). "Because of the strong role of Stat3 and NF-kB in SCC, and the dramatic effect of ACA against skin tumor promotion, we hypothesized that the effects of ACA may be modulated through Stat3 and/or NF-κB signaling." (PMID 22704648, 2012). "To further elucidate the role of Stat3 in skin cancer development, we first examined the Stat3 status in NHEKs, non-tumorigenic, spontaneously transformed keratinocyte cells (HaCaT) and two aggressive skin SCC cell lines (SRB1-m7 and SRB12-p9)." (PMID 16603078, 2006). "Although the role of AFs and IL-6 in skin cancer has not been extensively studied, our findings show that prenatally AFs release IL-6, which promotes the phosphorylation of JAK2 and STAT3 in KSCs." (PMID 38519574, 2024).
ischemia (74 papers, 2011 to 2025). A hypoperfusion of the BLOOD through an organ or tissue caused by a PATHOLOGIC CONSTRICTION or obstruction of its BLOOD VESSELS, or an absence of BLOOD CIRCULATION. "Knocking down NEAT1 inhibits the Akt/STAT3 signaling pathway, promotes M2-type polarization of microglia, inhibits M1-type polarization, and ultimately reduces neuronal apoptosis caused by ischemia." (PMID 37361996, 2023). "We detected the STAT3 and Gpc6 genes that are associated with synapse formation in astrocytes after ischemia." (PMID 34122124, 2021). "Signal transducer and activator of transcription 3 has been implicated in protecting the heart from acute myocardial injury due to ischemia and ischemia–reperfusion." (PMID 26664907, 2015). "We have shown here that 3 cycles of IPRE are associated with a significant increase in the phospho-STAT3/STAT3 ratio in the sham-operated animals 2 h after the end of the index ischemia in both sexes, which is in line with the literature data despite the late time-point." (PMID 34488888, 2021). "Our investigation demonstrated that JB inhibited the phosphorylation of JAK2 and STAT3, thereby blocking the JAK2/STAT3 signaling pathway, promoting M2 polarization of microglia, and alleviating ischemia–reperfusion injury." (PMID 41254929, 2025). "A previous study has shown that the JAK2/STAT3 pathway plays a vital role in hepatic ischemia/reperfusion injury." (PMID 40141803, 2025). "In the hyperacute phase, astrocytes are activated in response to TNF, microglia engage in phagocytosis, and there is an increase in Stat3‐induced ischemia‐responsible OPCs and senescent LECs." (PMID 40799188, 2025). "The heightened expression of STAT3 in NFH suggests its necessity in fostering new blood vessel formation to alleviate ischemia in necrotic regions and aid in repairing damaged areas." (PMID 40308566, 2025). "SPRC has been shown to promote angiogenesis in models of myocardial ischemia, activating VEGF expression by acting on STAT3 and providing a new target for ischemia/reperfusion heart disease therapy." (PMID 38434762, 2024). "Similar to NF-κB, phosphorylated STAT3 not only inhibits ferroptosis in intestinal ischemia/reperfusion-induced acute lung injury by positively regulating SLC7A11, but also induces ferroptosis in hypertensive mice by inactivating the SLC7A11/GPX4 signaling." (PMID 37153794, 2023). "It is reported that salvianolic acids promoted angiogenesis and neurological recovery by regulating STAT3 signaling pathway after ischemia." (PMID 36778026, 2023). "We show that inhibition of STAT3, as occurs during ischemia, is sufficient to induce endothelial dysfunction measured by response to ACh and barrier integrity." (PMID 36293020, 2022). "Overall, STAT3-miRNA crosstalk plays pivotal role in regulating the protective or injured cardiac response during ischemia/hypoxia injury." (PMID 36148063, 2022). "Inflammatory factors have been shown to activate the NF-kB signaling pathway, leading to the A1 phenotype of astrocytes, while ischemia stimulates the A2 state of astrocytes via signal transducer and activator of transcription 3 (STAT3) transcription factor." (PMID 36052093, 2022). "Phosphorylation and activation of STAT3 have been widely observed in the heart after ischemia or Ischemia/Reperfusion I/R." (PMID 36225565, 2022). "Functionally, we demonstrate that inhibiting STAT3 in ECs is sufficient to increase endothelial barrier permeability and decrease response to ACh, mimicking the effect of ischemia." (PMID 36293020, 2022). "The serum levels of interleukin (IL)-17A and IL-21 were decreased, and the expression of JAK2/STAT3 proteins was inhibited in all RJQM treatment groups compared to the ischemia group." (PMID 36034959, 2022). "In summary, we have demonstrated that a novel angiogenic IL-21/IL-21R/miR-30b/STAT3 promotes endothelial cell survival under ischemia in PAD." (PMID 35008699, 2021).